GSTO2 (glutathione S-transferase omega 2)
Description:
Exhibits glutathione-dependent thiol transferase activity. Has high dehydroascorbate reductase activity and may contribute to the recycling of ascorbic acid. Participates in the biotransformation of inorganic arsenic and reduces monomethylarsonic acid (MMA).
Synonyms: GSTO 2-2; bA127L20.1
Tractability: PROTAC: ubiquitination databases record sites on it.
Target class: Enzyme
Gene: Protein-coding gene on chromosome 10 (104,268,873 to 104,304,950, forward strand). Ensembl gene ENSG00000065621.
Subcellular location (Human Protein Atlas): Nucleoli; Nucleoplasm
Pathways (Reactome):
Metabolism: Glutathione conjugation; Vitamin C (ascorbate) metabolism
Gene Ontology:
Molecular function: glutathione dehydrogenase (ascorbate) activity; glutathione transferase activity; identical protein binding; oxidoreductase activity; protein binding; methylarsonate reductase activity
Biological process: cellular response to arsenic-containing substance; L-ascorbic acid metabolic process; xenobiotic metabolic process; glutathione metabolic process; cellular oxidant detoxification
Cellular component: extracellular exosome; cytoplasm; cytosol; perinuclear theca
Genetic constraint (gnomAD): Loss-of-function variants: 17 observed, 20.59 expected, observed/expected ratio (o/e) 0.83, 90% interval 0.56 to 1.24. The upper end of that interval is the gene's LOEUF score, 1.24, which puts it in group 5 of 6, group 1 being the genes least tolerant of losing a copy. Missense variants: 231 observed, 241.03 expected, observed/expected ratio (o/e) 0.96, 90% interval 0.86 to 1.07. Synonymous variants: 84 observed, 91.78 expected, observed/expected ratio (o/e) 0.92, 90% interval 0.77 to 1.1.
Homologues: Orthologues: chimpanzee GSTO2 (98% identical), macaque GSTO2 (97% identical), rabbit GSTO2 (91% identical), pig GSTO2 (87% identical), guinea pig GSTO2 (87% identical), dog GSTO2 (86% identical), rat Gsto2 (85% identical), mouse Gsto2 (84% identical), tropical clawed frog tlr12 (47% identical), tropical clawed frog gsto1 (44% identical), Drosophila melanogaster se (38% identical), Drosophila melanogaster GstO3 (35% identical), and 38 more. Paralogues in human: GSTO1 (64% identical), GSTZ1 (23% identical), GSTT4 (18% identical), CLIC1 (17% identical), CLIC6 (17% identical), CLIC4 (16% identical), CLIC5 (16% identical), CLIC2 (16% identical), CLIC3 (15% identical), GSTT2 (14% identical), GSTT2B (14% identical), GDAP1 (14% identical), and 2 more.
Diseases named in the same sentence as GSTO2 in open-access papers:
GSTO2 is named in the same sentence as 58 diseases in open-access papers, as found by Europe PMC text mining. Sharing a sentence is not in itself a finding about the gene and the disease. The quoted sentences say what the papers report.
bladder cancer (4 papers, 2013 to 2025). "Among GSTOs, only the GSTO2*N142D (A424G) was analyzed, and a significative association of the minor variant with the bladder cancer risk was found, independently of an arsenic exposure." (PMID 40724836, 2025). "GSTO1 (rs4925) and GSTO2 (rs156697) genotypes have been associated with worse prognosis and shorter survival in bladder cancer patients." (PMID 31924810, 2020). "GSTT1 active, GSTO1 Asp140Asp or GSTO2 Asp142Asp genotypes were independent predictors of a higher risk of death among bladder cancer patients (HR = 2.5, P = 0.028; HR = 2.9, P = 0.022; HR = 3.9, P = 0.001; respectively) and significantly influenced the overall survival." (PMID 24040330, 2013). "Polymorphisms: GSTO2*N142D (A424G; rs156697) and other GSTs (GSTP1, GSTM1, GSTT1, GSTZ1)Main findings:- positive association between GSTO2*N142D variant and bladder cancer risk independently of arsenic exposure." (PMID 40724836, 2025). "In the present study, we investigated the possible association between SNPs in the GSTP1, GSTO1, GSTO2, and ABCB1 genes with response to treatment in patients with bladder cancer." (PMID 26354850, 2015).
COVID-19 (4 papers, 2022 to 2025). A disease caused by infection with severe acute respiratory syndrome coronavirus 2. "Haplotype analysis confirmed a high degree of linkage disequilibrium between GSTO1 and GSTO2 polymorphisms, and the cumulative presence of risk genotypes further increased the probability of developing COVID-19." (PMID 40867811, 2025). "The data obtained showed that individuals carrying variant GSTO1*AA and variant GSTO2*GG genotypes exhibit higher odds of COVID-19 development, contrary to ones carrying referent alleles (p = 0.044, p = 0.002, respectively)." (PMID 35330457, 2022). "The distribution of polymorphisms in ACE2 (rs4646116), GSTO1 (rs4925) and GSTO2 (rs156697) were assessed in 255 COVID-19 patients and 236 matched healthy individuals, emphasizing their individual and haplotype effects on disease development and severity." (PMID 35330457, 2022). "Since both GSTO1 and GSTO2 genes are located on the same chromosome, the influence of their polymorphisms on the risk of COVID-19 development was further analyzed by a haplotype analysis." (PMID 35330457, 2022). "Carriers of H2 haplotype, comprising GSTO1*A and GSTO2*G variant alleles were at 2-fold increased risk of COVID-19 development (p = 0.002)." (PMID 35330457, 2022). "Carriers of H2 haplotype, comprising GSTO1*A and GSTO2*G variant alleles, revealed 2-fold increased odds of COVID-19 development." (PMID 35330457, 2022). "In the analysis of given polymorphisms, both GSTO1 (rs4925) and GSTO2 (rs156697) reached statistically significant association with the risk of COVID-19 development." (PMID 35330457, 2022). "Assuming the specific roles of GSTO enzymes in these processes, our results support the hypothesis that GSTO polymorphisms are associated with the risk of COVID-19, with special emphasis on the GSTO2-variant genotype." (PMID 35330457, 2022). "Indeed, the data obtained showed that individuals carrying variant GSTO1*AA (rs4925) and variant GSTO2*GG (rs156697) genotypes exhibit higher odds of COVID-19 development, contrary to ones carrying referent alleles." (PMID 35330457, 2022). "Therefore, the aim of our study was to assess the distribution of genetic polymorphisms in genes encoding ACE2 (rs4646116), GSTO1 (rs4925) and GSTO2 (rs156697) in COVID-19 patients." (PMID 35330457, 2022). "Indeed, we found that the polymorphisms in GSTP1, GSTM3, GSTO1 and GSTO2 genes were associated with significant odds of COVID-19 development, while the combined GSTP1 and GSTM3 genotype even exhibited cumulative risk regarding both COVID-19 occurrence and COVID-19 severity." (PMID 35624818, 2022). "Conversely, Djukic reported a statistically significant increase in the risk of developing COVID-19 in individuals with specific GSTO polymorphisms, including the GSTO1 AA, GSTO2 AG, and GSTO2 GG genotypes." (PMID 40867811, 2025). "The combination of genotypes exhibiting the lowest odds of COVID-19 development (GSTO1*CC/GSTO2*AA/ACE2*TT) was denoted as a Reference category." (PMID 35330457, 2022). "Having in mind beneficial effects of vitamin C on COVID-19 patients, low DHAR activity in patients with both variant GSTO2 alleles may result in deficient vitamin C regeneration and accumulation of the oxidized form, dehydroascorbate, contributing to disruption of redox homeostasis." (PMID 35330457, 2022).
breast carcinoma (3 papers, 2021 to 2025). "Additionally, postmenopausal women with either heterozygous or wild-type GSTO2-2 genotypes had a lower breast cancer risk compared to those with the homozygous mutant GSTO2 genotype." (PMID 40724836, 2025). "Additionally, a subgroup analysis showed that the GSTO2 polymorphism was significantly associated with an elevated risk of breast cancer (GG vs. AA), specifically in the homozygote, recessive, and allelic comparison model." (PMID 40724836, 2025). "However, the presence of both GSTP1 and GSTO2 polymorphisms together was also found to be associated with an increased risk of breast cancer, particularly in premenopausal women." (PMID 40724836, 2025). "Therefore, in postmenopausal patients, an increased breast cancer risk is linked to the mutant GSTO2 genotype alone, whereas in premenopausal women, the combined presence of GSTP1 and GSTO2 may further elevate the risk." (PMID 40724836, 2025). "The results indicated that the presence of heterozygous GSTO2-2 (Asn/Asp) was significantly higher in breast cancer cases than in the control group." (PMID 40724836, 2025). "Nevertheless, in the study by Sharif, the authors found significant associations between the breast cancer risk and allele frequencies of both the variant A allele of GSTO1*A140D (C419A; rs4925) and the G allele of GSTO2*N142D (A424G; rs156697)." (PMID 40724836, 2025). "In the first study by Masoudi, the lack of an association between the breast cancer risk and GSTO2*N142D (A424G; rs156697) polymorphism was again confirmed." (PMID 40724836, 2025). "However, neither the heterozygous nor the wild-type GSTO2-2 genotype showed a significant overall association with breast cancer risk." (PMID 40724836, 2025). "Potential therapeutic inbreast cancer by regulating breast cancer-related genes,including SERPINE1, PGAP3, MAP3K1, MAPK1, GSTO2, VIM, SPARC, and FGF2." (PMID 37191432, 2023).
clear cell renal cell carcinoma (3 papers, 2019 to 2023). "We investigated the the prognostic significance of GSTO1 (rs4925) and GSTO2 (rs156697 and rs2297235) polymorphisms in clear cell renal cell carcinoma (ccRCC) patients." (PMID 31861116, 2019). "Our data on the association of GSTO2*G variant allele with increased risk of PC are in line with previous findings on ovarian, breast, bladder, and clear cell renal cell carcinoma." (PMID 33937322, 2021).
lung carcinoma (3 papers, 2023 to 2025). "A strong association of the GSTO2-2 gene and COPD with lung cancer was detected, suggesting that GSTO2-2 may be critical for developing cancer among patients with COPD." (PMID 40724836, 2025). "Moreover, GSTO-2-overexpressing cells formed smaller tumours and the incidence of liver metastasis was lower as compared to control cells in a subcutaneous xenograft lung cancer model using nude mice." (PMID 36701089, 2023). "Analysis of 15 GST isoforms of human lung cancer using the TCGA dataset showed GSTP1, GSTA2, GSTA5, GSTO2, and GSTZ1 were significantly upregulated in LUAD compared to corresponding normal tissues, suggesting their potential oncogenic effects on LUAD." (PMID 36709476, 2023).
ovarian carcinoma (3 papers, 2023 to 2025). A malignant neoplasm originating from the surface ovarian epithelium. "Polymorphisms:GSTO2*N142D (A424G; rs156697)Main findings: - increased risk of ovarian cancer in subjects with GSTO2*N142D (A424G) polymorphism." (PMID 40724836, 2025). "The results of our study have shown that homozygous carriers of the GSTO2 variant G allele are at an increased risk of ovarian cancer development in comparison to carriers of the referent genotype." (PMID 38732205, 2024). "However, although both GSTO1 and GSTO2 variant genotypes seem to increase the probability of developing OC, statistical analysis indicated the GSTO2*G allele as the ovarian-cancer-risk-associated one." (PMID 38732205, 2024). "GSTO2 is highly expressed in a wide variety of tumors, for example, urothelial carcinoma, head and neck cancer, bladder cancer, epithelial ovarian cancer, breast cancer, and hepatocellular carcinoma." (PMID 36688005, 2023). "More recently, a study of Serbian subjects confirmed that homozygous carriers of the GSTO2*N142D variant have an increased risk of ovarian cancer, whereas carriers of the H4 haplotype (i.e., GSTO1*A variant allele and GSTO2*A wild-type allele) have a lower OC risk." (PMID 40724836, 2025).
Parkinson disease (3 papers, 2012 to 2020). A progressive degenerative disorder of the central nervous system characterized by loss of dopamine producing neurons in the substantia nigra and the presence of Lewy bodies in the substantia nigra and locus coeruleus. "Genetic polymorphisms in human GSTO1 and GSTO2 genes have been implicated in neurodegenerative diseases such as Alzheimer's and Parkinson's, and the levels of GSTO2 expression were described to be reduced in patients affected by these pathologies." (PMID 30723534, 2019). "Moreover, in the Drosophila model of Parkinson’s disease (PD) induced by the loss of the parkin gene, GstO2 modulates the mitochondrial ATP synthase activity." (PMID 32674363, 2020). "Furthermore, single-nucleotide polymorphisms (SNPs) in human GSTO1 and GSTO2 have been associated with the age at onset of Alzheimer’s disease (AD) and Parkinson’s disease (PD)." (PMID 32674363, 2020). "Glutathione S-transferase omega-1 and 2 genes (GSTO1, GSTO2), residing within an Alzheimer and Parkinson disease (AD and PD) linkage region, have diverse functions including mitigation of oxidative stress and may underlie the pathophysiology of both diseases." (PMID 22494505, 2012).
prostate carcinoma (3 papers, 2021 to 2024). A carcinoma that arises from epithelial cells of the prostate gland. "GSTO2 polymorphisms were found in patients with prostate cancer, and we showed medium to high levels of GSTO2 in PRAD samples." (PMID 39594421, 2024). "Considering the pleiotropic roles of glutathione transferase (GST) omega class members in redox homeostasis, we hypothesized that polymorphisms in GSTO1 and GSTO2 might contribute to prostate cancer (PC) development and progression." (PMID 33937322, 2021). "Haplotypes of GSTO1 rs4925 and GSTO2 rs156697 in relation to the risk of prostate cancer." (PMID 33937322, 2021). "We used the HPA database to explore the protein level of GSTO2 and found that it was lowest in skin cancer and highest in prostate cancer." (PMID 36688005, 2023). "The result indicated that the protein level of GSTO2 was lowest in skin cancer and highest in prostate cancer." (PMID 36688005, 2023). "Gene polymorphisms of GSTM1, GSTT1, GSTO1 rs4925, GSTO2 rs156697, GSTP1 rs1695, and GSTP1 rs1138272 and risk of overall mortality in prostate cancer patients by Cox proportional hazards regression models." (PMID 33937322, 2021).
Alzheimer disease (2 papers, 2021 to 2024). A progressive, neurodegenerative disease characterized by loss of function and death of nerve cells in several areas of the brain leading to loss of cognitive function such as memory and language. "Human GWAS indicates GSTO2 may be involved in both the risk and age-of-onset of Alzheimer’s Disease." (PMID 34324001, 2021).
cervical cancer (2 papers, 2018 to 2025). A primary or metastatic malignant neoplasm involving the cervix. "This study investigated the association between GSTO1 A140D and GSTO2 N142D polymorphisms and susceptibility to HPV infection and cervical cancer progression in Iranian women." (PMID 30115608, 2018). "Only one study focused on GSTO1-1 and GSTO2-2 in cervical cancer in Iranian women." (PMID 40724836, 2025).
diabetes (2 papers, 2022 to 2023). "When GST genotypes’ distribution in diabetes patients and controls was assessed in the subgroups with and without diabetic nephropathy, a significant association was found only for GSTO2 rs156697 polymorphisms." (PMID 36676788, 2023). "When the GST genotypes’ distribution in diabetes patients was assessed in the subgroups with and without diabetic nephropathy, a significant association was found only for the GSTO2 rs156697 polymorphism." (PMID 36676788, 2023).
Hepatic failure (2 papers, 2013 to 2016). "Statistical analyses showed a significant association between GSTO2 (N142D) polymorphism and hepatic failure that led to LT." (PMID 25013648, 2013). "The GSTO2 ND (OR=1.61, 95% CI: 1.14–2.27, p=0.007) and DD (OR=1.8, 95% CI: 1.10–2.95, p=0.02) genotypes were associated with an increased risk of developing hepatic failure that led to LT as compared to NN genotype." (PMID 25013648, 2013). "In 2013, we showed that patients with D allele of GSTO2 are more prone to develop hepatic failure." (PMID 27721965, 2016). "Therefore, we conducted this study to investigate the association between GSTO2 genetic polymorphism and the susceptibility of hepatic failure that would lead to liver transplantation." (PMID 25013648, 2013). "GSTO2 (N142D) is a member of this family the polymorphism of which may influence the metabolism of active components and free radicals and may contribute to hepatic failure." (PMID 25013648, 2013). "However, the association of GSTO2 polymorphism and hepatic failure that would lead to LT has not yet been examined." (PMID 25013648, 2013). "The association of GSTO2 (N142D) and hepatic failure has not been examined so far." (PMID 25013648, 2013).
hepatocellular carcinoma (2 papers, 2013 to 2023). A malignant tumor that arises from hepatocytes. "Several studies have shown that the polymorphism of GSTO2 has a role in the colorectal, gastric and hepatocellular carcinoma." (PMID 25013648, 2013).
lung squamous cell carcinoma (2 papers, 2023 to 2025). "Sumiya R revealed that GSTO2 is uniquely expressed in various lung stem cells but silenced in lung squamous cell carcinoma (LSCC) due to DNA hypermethylation." (PMID 40171042, 2025). "On the other hand, β-catenin expression was suppressed after induction of glutathione S-transferase omega-2 (GSTO-2), an enzyme that exhibits thioltransferase activity, in a lung squamous cell carcinoma model." (PMID 36701089, 2023).
proteinopathies (2 papers, 2020 to 2022). "Our findings demonstrated that GstO2 was a pathogenic regulator of TAF15-associated proteinopathies." (PMID 36411469, 2022). "Taken together, these findings indicated that GstO2 provided neuroprotection against the pathogenesis of TDP-43-associated proteinopathies." (PMID 32674363, 2020). "Therefore, GstO2 may play a protective role in the neuronal cells of Drosophila by suppressing the excessive ROS production from mitochondria in TAF15-associated proteinopathies." (PMID 36411469, 2022).
renal cell carcinoma (2 papers, 2024 to 2025). "On the other hand, the GSTO2*A424G polymorphism (rs156697) has been shown to be associated with ovarian, breast, urinary bladder, and renal cell cancers, which is in agreement with the results of our study." (PMID 38732205, 2024).
skin cancer (2 papers, 2023 to 2025). "Among GSTOs, only the GSTO2*N142D polymorphism was evaluated in subjects affected by different types of skin cancers, i.e., squamous cell carcinomas, basal cell carcinoma, malignant melanomas, and non-malignant lesions (benign)." (PMID 40724836, 2025).
chronic angle-closure glaucoma (1 paper, 2021). "This study aimed to identify the association of TGF-β1 (869T > C) and GSTO2 (142N > D) polymorphisms with two common types of glaucoma (including primary open-angle glaucoma (POAG) and chronic angle-closure glaucoma (CACG)) in the Iranian population." (PMID 34858663, 2021).